IL6 (interleukin 6)
Diseases named in the same sentence as IL6 in open-access papers (continued):
Sharing a sentence is not in itself a finding about the gene and the disease.
Insulin resistance (continued). "RJ also significantly reduced the TNF and IL-6 levels in the adipose tissue of the HFD-fed rats, potentially attributable to its anti-inflammatory effects or its role in ameliorating insulin resistance." (PMID 39339774, 2024). "IL‐6 and TNF exert inhibitory effects on the expression of glucose transporter type 4 (GLUT‐4), potentially promoting insulin resistance when their levels rise." (PMID 38874882, 2024). "This interaction between IL-6 and GSH insufficiency disrupts insulin signaling, promoting insulin resistance and impaired glucose metabolism." (PMID 39857603, 2024). "Future research should focus on elucidating the precise molecular mechanisms by which MMP-9, IL-6, IL-1, and GDF-15 derived from macrophages exert their effects on muscle atrophy and insulin resistance." (PMID 38044678, 2024). "It is important to note that the effects of MMP-9, IL-6, IL-1, and GDF-15 on muscle atrophy and insulin resistance are complex and intertwined." (PMID 38044678, 2024). "Our studies suggest that IL-6 inhibitors can significantly reduce type 2 diabetes, potentially through the inhibition of the JAK-STAT signaling pathway, thereby alleviating insulin resistance." (PMID 39229261, 2024). "This modulation regulates pathways involved in upregulating the expression of pro-inflammatory genes (IL-6, TNF-α, monocyte chemoattractant protein-1), linking metabolic disorders such as insulin resistance, glucose homeostasis, and inflammatory response." (PMID 38638434, 2024). "In addition, the higher level of concentrations of adipocytokines are associated with fluctuations in the levels of angiotensinogen, plasminogen activator inhibitor-1, interleukin-6, and resistin, which might progress the onset of insulin resistance and atherosclerotic lesions." (PMID 38536210, 2024). "These M1 macrophages enhance the production of proinflammatory cytokines (such as IL-6, IL-12, and TNF-α), which impede the insulin action on adipocytes, linking inflammation with insulin resistance." (PMID 39273520, 2024). "Effects on fasting glucose and insulin, Homeostatic Model Assessment of Insulin Resistance (HOMA-IR), HbA1c, adiponectin, leptin, IL-6, TNF-α, and C-reactive protein (CRP) in exercise vs control groups were analyzed using random effects meta-analysis." (PMID 38253590, 2024). "In NAFLD and NASH, insulin resistance and inflammatory cytokines, such as TNF-α and IL-6, are key drivers, with miR-122 and miR-34a playing significant roles in lipid metabolism and inflammation." (PMID 38928187, 2024). "I3S1DF significantly reduced the FBG level, improved the mice glucose tolerance, decreased insulin resistance and reduced the serum LDL-C, UA and IL-6 levels, indicating that I3S1DF can alleviate lipid metabolism abnormalities in obese mice." (PMID 39599608, 2024). "Proinflammatory cytokines, such as interleukin-6 (IL-6, IL-1) and tumor necrosis factor-α (TNF-α) play significant roles in the development of insulin resistance and hyperglycemia in trauma patients." (PMID 39682557, 2024). "These vesicles often carry inflammatory cytokines like IL-6 and TNF-α, which interfere with insulin signaling pathways, contributing to insulin resistance." (PMID 39796048, 2024). "The finding may also suggest that IL-6 plays a role in the pathophysiology of T2D, potentially contributing to hyperinsulinemia and perpetuation of the early stages of beta cell hyperfunction in the context of insulin resistance, as well as to β-cell exhaustion and overt diabetes." (PMID 38667300, 2024). "Functional enrichment analysis showed that SOCS3, IL6, FOXO1, CEBPB, SOX9, and PPARGC1A were mainly involved in the adipocytokine signaling pathway, insulin resistance, FoxO signaling pathway, AMPK signaling pathway, and PI3K-Akt signaling pathway." (PMID 38415055, 2024).
Insulin resistance (continued). "Chronic hepatic activation of the NF-κB pathway can induce IL-6-mediated insulin resistance; TNF-α inhibition decreases liver fatty acid oxidation and insulin resistance by Kupffer cell activation." (PMID 38672744, 2024). "Obese individuals have a higher serum level of IL-6, which is correlated with the development of metabolic syndrome, insulin resistance, and T2DM due to the capability of IL-6 to downregulate the gene expression of GLUT-4 and IRS-1." (PMID 37576807, 2023). "Central obesity, which forms the basis of insulin resistance and the metabolic syndrome, results in the production of pro-inflammatory cytokines such as tumor necrosis factor alpha (TNF-α) and interleukin-6 (IL-6)." (PMID 36830898, 2023). "An increase in the concentration of plasma CRP, IL-6, and TNF-α are reported in metabolic syndromes, including cardiovascular diseases and insulin resistance." (PMID 38155869, 2023). "In this study, HFD-enhanced TNF-α, ox-LDL, IL-6, and MMP-9 levels, whereas SG markedly downregulated proinflammatory cytokines and reversed insulin resistance, resulting in vascular protection." (PMID 36982743, 2023). "Insulin resistance plays an vital role in NAFLD pathogenesis, and various inflammatory factors such as IL-6 and TNF-α can promote insulin resistance, leading to NAFLD occurrence and development." (PMID 36778868, 2023). "Adiponectin has hepatoprotective effects due to its ability to reduce inflammation, inhibiting the release of proinflammatory cytokines such as IL-6 and TNF-α and improving insulin resistance." (PMID 37998747, 2023). "It is associated with elevated inflammatory markers, such as C-reactive protein, interleukin 6 (IL-6) and tumor necrosis factor (TNF), which can increase insulin resistance." (PMID 36810280, 2023). "It has been suggested that Il-6 and TNF-alpha are involved in the pathogenesis of insulin resistance and type 2 diabetes by inhibiting insulin receptor tyrosine phosphorylation and reducing insulin production in pancreatic beta cells." (PMID 37509592, 2023). "On the other hand, adiposity leads to the production of proinflammatory cytokines such as interleukin-6 (IL-6), interleukin 1-β (IL-1β), and tumor necrosis factor-alpha (TNF-α), which are closely related to renal cell dysfunction and insulin resistance." (PMID 37786577, 2023). "This in turn triggers pro-inflammatory macrophage aggregation, Treg cell reduction, and IL-6 and TNF-α secretion increases, leading to systemic inflammation, insulin resistance, oxidative stress, and a series of metabolic reactions." (PMID 36843589, 2023). "The ratio of M1-like to M2-like macrophages is increased substantially resulting in copious secretion of proinflammatory mediators such as TNFα, IL-6, IL-1β, MCP-1, fetuin-A (FetA), etc. further worsening insulin resistance." (PMID 36718668, 2023). "FGF21 is a hormone that regulates glucose and lipid metabolism, while IL-6 and TNF-α are proinflammatory cytokines that play a role in insulin resistance." (PMID 37238961, 2023). "Individuals that are overweight and implemented a KD also had decreased body weight, insulin resistance, and serum markers of inflammation (e.g., TNF-α, IL-6, IL-8, MCP-1)." (PMID 36937529, 2023). "On the other hand, inflammatory cytokines, such as interleukin-6 (IL-6) and tumor necrosis factor-alpha (TNF-α), can affect insulin sensitivity, glucose, and lipid metabolism, potentially leading to insulin resistance." (PMID 37841266, 2023). "It has been shown that the inflamed adipose tissue of obese individuals releases a variety of cytokines, such as IL-18, IL-6, IL-1, and TNF-α, thereby contributing to obesity-induced insulin resistance." (PMID 37876013, 2023). "Pro-inflammatory cytokines like IL-6 and TNF-α, induce insulin resistance by inhibiting the signals of insulin receptors, thereby increasing the risk of type-2 diabetes." (PMID 38155869, 2023).
Insulin resistance (continued). "Hesperidin treatment also improved insulin resistance (Homeostasis model of insulin resistance (HOMA-IR) values) and reduced pro-inflammatory markers TNF-α and IL-6 levels." (PMID 38234970, 2023). "Insulin resistance (HOMA-IR, QUICKI), HOMA-β and elevations in plasma inflammatory cytokine levels (TNF-α, IL-6 and HMGB-1) were all attenuated by galantamine." (PMID 37731032, 2023). "Therefore, increases in plasma LPS and pro-inflammatory cytokines such as interleukin-6 (IL-6) or tumor necrosis factor-α (TNF-α) levels could lead not only to insulin resistance but also to decreased Sg, both of which may result in postprandial hyperglycemia and subsequent reactive hypoglycemia." (PMID 37367911, 2023). "A recent study indicated that concentrations of tumor necrosis factor alpha (TNF-α) and interleukin 6 (IL-6) are higher in females with PCOS, especially among those cases that present with signs of insulin resistance." (PMID 37569074, 2023). "It was also demonstrated that the liver adipose tissue secretes several proinflammatory factors, such as interleukin 6 (IL-6) and tumor necrosis factor alpha (TNF-α), which play a role in inducing systemic insulin resistance." (PMID 36834741, 2023). "Higher levels of interleukin 6 (IL-6) and tumor necrosis factor (TNF) α were found in patients with several features of MetS such as central obesity and insulin resistance, when compared to the general population." (PMID 38004150, 2023). "Our results that galantamine treatment reduced inflammatory cytokines (TNF-α, IL-6, HMGB-1), improved insulin resistance and glycemic control in the db/db mice are consistent with those of the clinical trial of galantamine in patients with metabolic syndrome." (PMID 37731032, 2023). "Our previous clinical study showed the effectiveness of Eriomin® in reducing fasting glucose, glucose intolerance, insulin resistance (HOMA‐IR), glycated hemoglobin (HbA1c), glucagon, C‐peptide, HSCRP, IL‐6, and TNF‐α." (PMID 37970408, 2023). "M1 macrophage accumulation in adipose tissue will produce various pro-inflammatory cytokines and chemokines that contribute to insulin resistance, such as tumor necrosis factor-alpha (TNF-α), interleukin 6 (IL-6), resistin, and leptin." (PMID 37104164, 2023). "Interleukin-6 (IL-6) and tumor necrosis factor-alpha (TNF-α), inflammatory molecules released during immune responses, can induce insulin resistance in peripheral tissues, particularly adipose tissue and the liver." (PMID 38140151, 2023). "Adipose tissue secretes proinflammatory cytokines, such as interleukin-6 (IL-6) and tumor necrosis factor-alpha (TNF-α), which contribute to insulin resistance and systemic inflammation." (PMID 37868505, 2023). "In the context of T2D, IL-6 and TNF-α are known to be upregulated, contributing to insulin resistance, impaired insulin-mediated glucose uptake in peripheral tissues, and endothelial dysfunction in T2D." (PMID 37892970, 2023). "Inflammatory cytokines, such as interleukin-6 (IL-6) and tumor necrosis factor-alpha (TNF-α), are increased in individuals with metabolic syndrome, and they contribute to the development of insulin resistance and other metabolic abnormalities." (PMID 37445955, 2023). "There is also evidence that SOCS3-mediated insulin resistance is involved in the upregulation of mediators (e.g. tumor necrosis factor-α (TNF-α), Interleukin 6 (IL6)) signaling pathways." (PMID 36609306, 2023). "Tumor necrosis factor-α and interleukin (IL)-6 are derivatives of acute-phase proteins, including CRP, and both potentially contribute to insulin resistance by affecting intracellular insulin signaling." (PMID 37448125, 2023). "Simultaneously, increased levels of adipokines and inflammatory cytokines (such as IL-1, IL-6 and TNF-α) activate NF-κB signaling pathway and promote insulin resistance." (PMID 37424859, 2023). "IL-1, IL-6, IL-17, IL-33, GATA-3, and other proinflammatory cytokines also play important roles in renal insulin resistance." (PMID 36776877, 2023).
Insulin resistance (continued). "Increased CT BoD, NLR, CRP, IL-6, PCT, insulin resistance indices, and hyperglycemia during hospitalization, as well as decreased PFR were associated with longer hospitalization." (PMID 37515156, 2023). "Palmitate, for example, as a saturated fatty acid, promotes cytokines secretion as IL-6 and TNF-α that can lead to insulin resistance and glucose intolerance." (PMID 36677559, 2023). "Circulating pro-inflammatory cytokines, such as IL-6 and TNF-α, can be promoted by TG deposition in adipose tissue; in turn, the amplifying inflammatory signal contributes to further adiposity and insulin resistance." (PMID 38201888, 2023). "Addition of SR1 significantly alleviated Kyn-induced insulin resistance as characterized by the increased p-AKTSer473 along with decreased STAT3, p-STAT3Tyr705 and reduced IL-6 secretion." (PMID 35715443, 2022). "Our results suggest that IRW and IQW reduced the levels of glucose, HDL, and LDL, improved GLU tolerance and insulin resistance induced by the HF diet, and decreased the mRNA expression of TNF-α, IL-6, and IL-1β." (PMID 36232527, 2022). "IL-6 and TNF-α can induce insulin resistance in the liver and adipocytes by reducing the phosphorylation of insulin receptor substrate (IRS) or by inhibiting IRS transcription." (PMID 36235858, 2022). "In the present study, the combination of W. coagulans and EA in food significantly reduced the plasma levels of endotoxins LPS, hs-CRP, Zonulin, TNF-α, and IL-6 and relieved HFD-induced insulin resistance." (PMID 36235858, 2022). "Increasing levels of chronic subclinical inflammatory markers, such as C-reactive protein (CRP) and interleukin-6 (IL-6), are thought to be involved in the development of T2DM via insulin resistance onset and insulin secretion disruption." (PMID 35682821, 2022). "Hepatic IL-6 expression is increased in animal models of nonalcoholic fatty liver disease (NAFLD), which results in insulin resistance in mice." (PMID 35453695, 2022). "In the obese state, ATM polarization is shifted towards M1 and M1 ATMs, which mainly upregulates monocytes’ chemoattractants, enhances adipocyte lipolysis and induces insulin resistance by secreting TNF-α and IL-6." (PMID 35052852, 2022). "Previous studies have revealed that interleukin-6 (IL-6) and tumour necrosis factor-α (TNF-α) are involved in insulin resistance; therefore, we explored the clinical significance between these insulin resistance-related factors and FFAs." (PMID 35711703, 2022). "Studies have shown that postoperative IL-6 and TNF-α values are positively correlated with insulin resistance." (PMID 35711703, 2022). "Numerous inflammatory cytokines and mediators, including tumor necrosis factor-α (TNF-α), interleukin-6 (IL-6) and monocyte chemoattractant protein 1 (MCP-1), are upregulated during insulin resistance." (PMID 35327570, 2022). "The systemic release of inflammatory cytokines such as IL-6 and TNF-α directly contributes to insulin resistance." (PMID 35326098, 2022). "Hypertrophic adipose tissue secretes inflammatory cytokines such as IL-6 and TNF-α, which involve the pathophysiology of metabolic diseases like increased insulin resistance." (PMID 35469126, 2022). "Selected stress and age related biological outcomes were insulin resistance (HOMA-IR), systemic inflammation (IL-6, CRP), and cellular aging (leukocyte telomere length)." (PMID 34357581, 2022). "Previously, the overproduction of IL-6 and TNF-α in T2DM patients led to the development of vascular inflammation and insulin resistance." (PMID 36276816, 2022). "Visceral fat accumulation induces the secretion of pro-inflammatory cytokines, including IL-6, TNF-α, and IL-8, which reduces insulin sensitivity and leads to hyperinsulinemia and even insulin resistance." (PMID 36474704, 2022). "Increased levels of inflammatory cytokines such as IL-1, IL-6, MCP-1, andleptin, and a decreased level of adiponectin are proposed to promote the developmentof insulin resistance and T2DM." (PMID 35976267, 2022).
Insulin resistance (continued). "In conclusion, all types of AA extracts (i.e. hot and cold-water and alcoholic), improved insulin resistance through reduction of LDL/HDL ratio, free fatty acids, TNF-alpha, and IL-6." (PMID 35145895, 2022). "Herein, we show that mHypoA-2/29 neurons exposed to pro-inflammatory microglial conditioned medium (MCM) showed higher expression of the pro-inflammatory cytokines IL-6, IL-1β, and TNF-α, in addition to developing insulin resistance." (PMID 35883638, 2022). "IL-6 can promote the production of TNF-α in the inflammatory response, whereas TNF-α from adipose tissue and placenta can promote insulin resistance in pregnant women, which is closely related to the pathogenesis of GDM." (PMID 35415242, 2022). "Subsequently, insulin resistance stemming from excessive caloric intake can stimulate proinflammatory mediators and cytokines such as TNF-α, IL-6 and CRP." (PMID 35252372, 2022). "We noticed that the BSME decreased the expression levels of insulin resistance and macrophage chemoattractant proteins, such as TNF-α, IL-6, leptin and STAT-6, in maturing-adipocyte-secreted proteins." (PMID 35209178, 2022). "The amelioration of insulin resistance was claimed under the mechanism of regulating intestinal flora to reduce tumor necrosis factor-α (TNF-α), interleukin-6 (IL-6), and hypersensitive C-reactive protein (HS-CRP) in plasma." (PMID 35529925, 2022). "In diabetic and insulin-resistant conditions, elevated levels of TNF, IL-6, and IL-8 have all been recorded." (PMID 35276979, 2022). "Lastly, higher IL-38 levels were observed to be closely correlated with insulin resistance (INS, CpS, HOMA-IR, and QUICK), liver injury (AST and ALT), and inflammation [IL-6 and 25(OH)D]." (PMID 35948957, 2022). "IL-6 and TNF-α have an inhibitory effect on glucose transporter type-4 (GLUT-4) expression, and their increase leads to insulin resistance." (PMID 36355818, 2022). "In this study we found significant reductions in the exercise group compared with usual care in pro-inflammatory biomarkers including TNF-α, IL-6, IL-8, hs-CRP or leptin, and those related to insulin resistance." (PMID 35795051, 2022). "Cancer expansion triggers the release of proinflammatory cytokines such as IL-1, IL-6, and TNF-α, which in turn increase lipolysis, muscle breakdown, and insulin resistance." (PMID 36291801, 2022). "The body weight, insulin resistance index, and the levels of FBG, C-Peptide, IL-6, TNF-α, and MDA in the serum of HFD mice significantly decreased (P < 0.05)." (PMID 35571892, 2022). "Training increases the levels of the anti-inflammatory myokine IL-6, regulates redox homeostasis, corrects mitochondrial biogenesis mediated by PGC-1α, stimulates protein synthesis, and reduces insulin resistance." (PMID 35053505, 2022). "Adipose tissue inflammation, along with the increase of pro-inflammatory cytokines such as interleukin 6 (IL‐6) and tumor necrosis factor alpha (TNF‐α), also lead to insulin resistance." (PMID 35546181, 2022). "In obese people, IL-6 reduces the expression of glucose transporter-4 (GLUT4) and insulin receptor substrate-1 (IRS-1) and, thus, increases insulin resistance." (PMID 36013196, 2022). "There were significant decreases in insulin resistance, hyperinsulinemia, hyperglycemia, dyslipidemia, TNF-α, and IL-6 and concomitant increases in adiponectin and β-cell function." (PMID 36297570, 2022). "Higher levels of IL-6, TNF-α, and C reactive protein (CRP) have been found in diabetic patients, and it is known that high CRP levels are correlated to insulin resistance due to impaired intracellular insulin signaling." (PMID 35996409, 2022). "Sambucus nigra L. fruit extract alleviated insulin resistance by suppressing the enhanced production of NO, TNF-α, IL-6, and PGE2, where the presence of cyanidin-based anthocyanins, flavan-3-ols, flavonols, and hydroxycinnamic acids were detected." (PMID 35057523, 2022).